VGLL3 (vestigial like family member 3)
Diseases named in the same sentence as VGLL3 in open-access papers (continued):
Sharing a sentence is not in itself a finding about the gene and the disease.
cervical cancer (1 paper, 2022). A primary or metastatic malignant neoplasm involving the cervix. "Importantly, high levels of VGLL3 expression were shown to have a positive correlation with poor prognosis in various human cancers, such as breast, colon, ovarian, head and neck, pancreatic, renal, gastric and cervical cancers." (PMID 35366053, 2022). "Notably, VGLL3‐high groups showed poor prognosis in databases of various types of cancers such as breast, colon, ovarian, head and neck, pancreatic, renal, gastric and cervical cancer." (PMID 35366053, 2022).
Cirrhosis (1 paper, 2025). A chronic disorder of the liver in which liver tissue becomes scarred and is partially replaced by regenerative nodules and fibrotic tissue resulting in loss of liver function. "Furthermore, to preliminarily assess the detectability of VGLL3 in body fluid samples, we attempted to detect VGLL3 protein expression in the plasma of patients with cirrhosis by Western blot." (PMID 41008580, 2025). "Western blot analysis did not detect VGLL3 protein signals in the plasma of patients with cirrhosis, suggesting that its expression level in the blood is low or its stability is poor, which is not conducive to its application as a circulating biomarker." (PMID 41008580, 2025).
Duchenne muscular dystrophy (1 paper, 2019). Duchenne muscular dystrophy (DMD) is a neuromuscular disease characterized by rapidly progressive muscle weakness and wasting due to degeneration of skeletal, smooth and cardiac muscle. "VGLL3 is also differentially expressed human patients with muscle-related disease, with a >3-fold increase in quadriceps muscles of Duchenne muscular dystrophy patients." (PMID 31138678, 2019).
epithelial ovarian cancer (1 paper, 2023). "The correlation of VGLL3 in cancer proliferation, advanced tumor stage, grade, and poor prognosis has previously been reported in other cancers except for ovarian cancer." (PMID 37342190, 2023).
gastric tumor (1 paper, 2020). "VGLL3-high gastric tumor showed the activation of the MAPK, JAK-STAT, and WNT pathways together with enhanced immune infiltrates." (PMID 32793503, 2020).
Insulin resistance (1 paper, 2024). Increased resistance towards insulin, that is, diminished effectiveness of insulin in reducing blood glucose levels. "We highlight two phospholipase encoding genes, PLA2G12A and PLA2G6, which liberate arachidonic acid and improve insulin sensitivity, and VGLL3, a transcriptional co-factor that increases insulin resistance partially through enhanced adiposity." (PMID 39277575, 2024). "Taken together, these data suggest that VGLL3 increases insulin resistance by altering adiposity." (PMID 39277575, 2024).
intracranial aneurysm (1 paper, 2024). "It is possible that VGLL3 may mitigate the incidence of intracranial aneurysms via its interaction with HDL." (PMID 38348744, 2024).
liver fibrosis (1 paper, 2023). "Significant reduction of collagen mRNA and Collagen I protein by Vgll3 knockdown was observed in cardiac myofibroblasts, as well as in liver myofibroblasts isolated from NASH model mice, and from mice with CCl4-induced liver fibrosis, or CCD-18Co cells." (PMID 36754961, 2023).
male infertility (1 paper, 2022). The inability of the male to effect fertilization of an ovum after a specified period of unprotected intercourse. "In cattle, variants in SEC16B, VGLL3, and DEBB119 were also associated with male infertility." (PMID 36140773, 2022).
non-alcoholic steatohepatitis (1 paper, 2023). "Vgll3 expression was also increased in the fibrotic liver of non-alcoholic steatohepatitis (NASH) model mice, specifically in hepatic stellate cells expressing Desmin." (PMID 36754961, 2023).
osteoarthritis (1 paper, 2017). A noninflammatory degenerative joint disease occurring chiefly in older persons, characterized by degeneration of the articular cartilage, hypertrophy of bone at the margins and changes in the synovial membrane. "Curiously, VGLL3 gene was also found to be significantly higher in human cartilage presenting endemic osteoarthritis, suggesting its implication in cartilage development." (PMID 28870996, 2017).
ovarian tumor (1 paper, 2020). "The tumor suppressor role of VGLL3 was also suggested in ovarian tumor." (PMID 32793503, 2020).
preeclampsia (1 paper, 2026). Preeclampsia is a hypertensive disorder of pregnancy that is characterized by new-onset hypertension with proteinuria presenting after 20 weeks of gestation, and depending on mild or severe forms may initially present with severe headache, visual disturbances, and hyperreflexia. "Our data reveal that VGLL3 acts upstream of preeclampsia-associated processes, including the production of sFLT1 (soluble fms-like tyrosine kinase 1), a key biomarker of the disease." (PMID 41953989, 2026).
psoriasis (1 paper, 2022). An autoimmune condition characterized by red, well-delineated plaques with silvery scales that are usually on the extensor surfaces and scalp. "In psoriasis, estrogen might exert its functions by modulating the expression of certain genes like sex-biased transcription co-factor vestigial-like protein 3 (Vgll3) and CCAAT enhancer binding protein beta (cebpb), microRNAs (miR146a, 21 and 210), and chemokines (CCL5 and CXCL10)." (PMID 35663991, 2022). "Estrogen has significantly increased the expression of Vgll3 and cebpb genes, which were earlier shown to regulate keratinocyte secreted IL-17 family of cytokines, as well as other chemokines and cytokines suggesting a possible involvement of these genes in estrogen promoted psoriasis." (PMID 35663991, 2022).
skin cancer (1 paper, 2025). "Although it is known that males develop more skin cancer than females and that YAP1 is upregulated in many skin cancers, a direct connection between VGLL3 and YAP1 in skin cancer has not yet been identified." (PMID 40741215, 2025).
systemic sclerosis (1 paper, 2024). A chronic disorder, possibly autoimmune, marked by excessive production of collagen which results in hardening and thickening of body tissues. "We identify the Hippo pathway as a potential therapeutic target in systemic sclerosis, and describe its role in both myofibroblast and EndoMT transition, two key cellular events in SSc pathogenesis, and provide a link with the sex-biased Hippo pathway regulator VGLL3." (PMID 38172207, 2024).
tumor (21 papers, 2011 to 2025). "Immunologically, VGLL3 has been shown to be associated with the abundance of macrophages and dendritic cells in tumor infiltrates." (PMID 38726338, 2024). "Genetic analysis of untreated xenograft tumors implicated VGLL3 as a novel oncogene involved in tumor growth." (PMID 38213996, 2024). "This study demonstrated that VGLL3 has potential prognostic value in HGSOC because its overexpression was shown to be associated with advanced tumor stage and poor prognosis." (PMID 37342190, 2023). "For example, the Cox proportional-hazards model associates the MR VGLL3 with a worse prognosis and the Fisher test associates VGLL3 with Diffuse tumors and a greater tumor mass (TNM:T), according to a previous report." (PMID 36230884, 2022). "Further, VGLL3 expression was significantly associated with tumor infiltrating macrophages." (PMID 37342190, 2023). "This suggested that VGLL3 may activate or inhibit immune cells infiltrating the tumor, although the underlying mechanism involved is unknown." (PMID 31992826, 2020). "The Log-rank test and Kaplan-Meier survival analysis showed that high levels of VGLL3 and macrophages were significantly associated with poor survival (P < 0.05), whereas tumor purity, B cells, CD8+ T cells, CD4+ T cells, neutrophils, and dendritic cells were not (P > 0.05, data not shown)." (PMID 31992826, 2020). "Therefore, we hypothesized that VGLL3 expression was associated with immune cell infiltration and tumor-associated macrophages." (PMID 31992826, 2020). "In tumor cells, VGLL3 expression leads to the inactivation of YAP/TAZ and the combination of VGLL3 with TEAD expression promotes expression of Hippo pathway genes." (PMID 38726338, 2024). "VGLL3 mRNA expression was significantly correlated with both advanced tumor stage and poor overall survival (OS) (p=0.046 and p=0.003, respectively)." (PMID 37342190, 2023). "The results suggest that VGLL3 is an important factor for HGSOC that correlates with tumor progression and immune evasion." (PMID 37342190, 2023). "VGLL3 expression in parental OV90 cells was undetectable, and the transfer of the chromosome fragment rescued VGLL3 expression and repressed tumorigenicity, suggesting that VGLL3 is a tumor suppressor gene." (PMID 32793503, 2020). "In our study, we found that VGLL3 expression positively correlated with tumor heterogeneity regarding immune cell infiltration, particularly with CD8+ T cells, CD4+ T cells, macrophages, neutrophils, and dendritic cells, but not B cells." (PMID 31992826, 2020). "Univariate analysis showed that T cells and dendritic cells were favorable prognostic factors, while VGLL3 levels, neutrophils, B cells, macrophages, and tumor heterogeneity were detrimental prognostic factors." (PMID 31992826, 2020). "To summarize, VGLL3 has a potential prognostic and therapeutic value in STAD, because its overexpression was associated with advanced tumor stage, poor differentiation, TAM infiltration, and poor prognosis." (PMID 31992826, 2020). "Vgll3 as a new partner of ets1 was unexpected and is very challenging as ets1 is also a proto-oncogene and VGLL3 has been proposed to play a role in tumor progression." (PMID 28870996, 2017). "VGLL3 showed large Diff (delta Ct) discrepancies between the primary Gleason tumor pattern and the benign sample." (PMID 25296164, 2014). "Measurements of the gene signature in benign tissue revealed that IGFBP3 consistently provided similar values to those in the tumor tissue from the same patient, F3 remained similar but with larger variation, and VGLL3 was highly variable." (PMID 25296164, 2014). "where VGLL3 induction showed a tumor-suppressive phenotype in EOC." (PMID 37342190, 2023). "Despite the fact that there is a discrepancy in VGLL3 mRNA and protein expression between tumor and normal tissues, we interestingly observed that higher levels of both VGLL3 mRNA and protein expression among tumor tissues were associated with the worse OS in HGSOC." (PMID 37342190, 2023).
tumor (continued). "The concept of the tumor-suppressing role of VGLL3 needs more evaluation." (PMID 32793503, 2020). "Therefore, relationship between VGLL3-dependent cell growth and the tumor suppressive role of YAP/TAZ needs to be evaluated." (PMID 32793503, 2020). "In addition, VGLL3 was associated with the abundance of macrophages and dendritic cells in tumor infiltrates, of which only VGLL3 and macrophage counts were the independent prognostic factors of immune cell infiltration in the TIMER Database." (PMID 31992826, 2020). "In contrast, VGLL3 acts as a tumor suppressor in epithelial ovarian cancer." (PMID 31992826, 2020). "This might reflect that VGLL3 can have both proliferation-promoting oncoprotein or pro-differentiation tumour suppressor effects." (PMID 31138678, 2019). "Conversely, VGLL3 has been reported to act as a tumour suppressor in epithelial ovarian cancer." (PMID 31138678, 2019). "VGLL3 displays either a role in the tumor suppression pathway or has oncogenic properties." (PMID 28870996, 2017). "Therefore, VGLL3 is differentially expressed by sex in some tissues and alters tumor outcome." (PMID 34768683, 2021). "Therefore, we hypothesized that VGLL3 expression is associated with immune infiltration in STAD tumors, and a potential marker of the tumor immune microenvironment." (PMID 31992826, 2020). "For VGLL3, the comparability is poor, but it is unknown if this is related to this gene being differently expressed in tumor contra benign tissue, in epithelial cancer cells versus stromal cells or if this is simply an effect of the technical difficulties in measuring low expression levels." (PMID 25296164, 2014). "Of note, primary PCa tumours showed high JAG1, GP2, GLO1, NPR3, VGLL3, CHRNA2 and SEMA3F mRNA levels in primary PCa tissue samples." (PMID 40219635, 2025). "A four‐mRNA signature (CHRNA2, NPR3, VGLL3 and PAH) was found in primary tumour tissue samples from pN1 PCa patients, and then it was validated using the TCGA‐PRAD and GSE220095 datasets." (PMID 40219635, 2025). "Our initial genetic analysis of bulk tumor samples identified several novel candidate genes, including NEDD4L and VGLL3." (PMID 38213996, 2024). "Taken together, these findings suggest that the role of VGLL3 mRNA is distinctive in HGSOC compared to the other five genes, which correlated with the characteristics of advanced tumor stages of HGSOC and poor survival outcomes." (PMID 37342190, 2023). "To investigate this further, we performed mutation analysis in 1781T of protein coding regions and intron/exon splice junction sites of the top 3p12-pcen tumour suppressor gene candidates, ROBO1, GBE1 and VGLL3." (PMID 22163003, 2011). "Accordingly, we hypothesized that different CAF content in Ccne1+ and Vgll3+ tumors is responsible for their distinct immune TME, and especially for blocking T cells at the tumor border in the Ccne1+ tumors." (PMID 38509063, 2024). "By examining spatial distribution of the T cells in these two models, we observed that both CD8+ and CD4+ T cells are significantly more abundant in the inner parenchyma of Vgll3+ tumors than in Ccne1+ tumors, in which CD8+ T cells are instead especially restricted to the tumor margin." (PMID 38509063, 2024). "In line with previous reports, we found that VGLL3 expression in both mRNA and protein level was also correlated with advanced tumor stage and poor prognosis in HGSOC, suggesting that VGLL3 may promote the progression of HGSOC." (PMID 37342190, 2023). "When tumors were compared to normal ovarian samples, we found that VGLL3 was significantly lower in tumor samples than it was in normal ovarian samples in both the TCGA and GSE26712 cohorts (p<0.05 and p=2.4e-07, respectively)." (PMID 37342190, 2023). "We observed that the Entinostat-mediated ESR1 downregulation was only partially, but not completely, rescued by deletion of VGLL3, suggesting Entinostat has broader anti-tumour effect." (PMID 35217640, 2022).
tumor (continued). "Therefore, VGLL3 may be involved in TGF-β-related cell responses, such as epithelial-to-mesenchymal transition (EMT), in VGLL3-amplified or -high tumor cells." (PMID 32793503, 2020).
cancer (16 papers, 2014 to 2025). A tumor composed of atypical neoplastic, often pleomorphic cells that invade other tissues. "The association of VGLL3 with those pathways has been previously been reported in different cancers." (PMID 37342190, 2023). "VGLL3 was associated with four known and three novel cancer-related signalling pathways, thus implying that VGLL3 is involved in the deregulation of many genes and pathways." (PMID 37342190, 2023). "Now a day’s multiple pieces of evidence suggest that VGLL3 is associated with different cancers." (PMID 37342190, 2023). "VGLL3 was found to be associated with poor prognosis in various types of cancer patients." (PMID 35366053, 2022). "Therefore, we next examined the association of VGLL3 expression with the prognosis of human cancer patients using the PROGgeneV2 database." (PMID 35366053, 2022). "This indicates that persistent expression of VGLL3 induced malignant tumors in nude mice and is fundamental to an aneuploidy-mediated phenotype." (PMID 38732044, 2024). "Recognizing the significance of sex differences in the immune response to cancer, we initially conducted pilot experiments with male mice bearing Ccne1+ and Vgll3+ tumors, yielding comparable results in terms of immune composition and immune exclusion." (PMID 38509063, 2024). "We also investigated the role of VGLL3 as a prognostic factor of HGSOC and its association with cancer-related signal transduction pathways." (PMID 37342190, 2023). "In recent years, the role played by VGLL3 in cancers has attracted increasing research attention because of its dynamic behaviour in different cancers." (PMID 37342190, 2023). "The gene sets associated with high VGLL3 expression were enriched in extracellular matrix (ECM) receptor interaction, focal adhesion, pathways in cancer, MAPK signaling pathway, JAK STAT signaling pathway, ABC transporters, and the WNT signaling pathway." (PMID 31992826, 2020). "We investigated VGLL3-related pathways in cancer to explore the potential mechanism in HGSOC." (PMID 37342190, 2023). "Finally, the DEGs pathways and co-expressing genes identified in this study suggest the prospective molecular function of VGLL3 in cancer." (PMID 37342190, 2023). "Moreover, VGLL3 was associated with TAM infiltration, which is frequently observed in the immunosuppressive microenvironment of cancer." (PMID 37342190, 2023). "Furthermore, we found that VGLL3 expression correlated with poor prognosis in various types of cancer patients." (PMID 35366053, 2022). "Consistent with this hypothesis, our data showed that VGLL3 expression was positively correlated with poor prognosis in various types of cancer patients." (PMID 35366053, 2022). "Although VGLL3 is known to be highly expressed and stimulate cell proliferation in mesenchymal cancer cells, its involvement in mesenchymal phenotypes is largely unknown." (PMID 35366053, 2022). "VGLL3 is highly expressed in mesenchymal cancer cells, such as MDA‐MB‐231 cells." (PMID 35366053, 2022). "Together, these results demonstrated that VGLL3 was involved in cancer-related KEGG pathways." (PMID 31992826, 2020). "Furthermore, because VGLL3 expression is affected by epigenetic status, epigenetic changes in cancer cells may be involved in its expression." (PMID 35366053, 2022). "Among those with the highest enrichment score, the regulon VGLL3, an unfavorable prognostic marker in GC, resulted in the highest association with EMT in Diffuse GCs as well as with the invasiveness signature resulting from the interactions between cancer cells and the microenvironment." (PMID 36230884, 2022). "Therefore, it is reasonable to speculate that VGLL3 is involved in EMT phenotypes during cancer progression." (PMID 35366053, 2022). "Moreover, VGLL3 expression is high in ARMS associated with PAX3-FOXO1 and PAX7-FOXO1 fusion genes when compared to other cancers and controls." (PMID 31138678, 2019).
cancer (continued). "We further reveal that TEAD inhibition or YAP/TAZ silencing leads to VGLL3-mediated transcriptional activation of SOX4/PI3K/AKT signaling axis, which contributes to cancer cell survival and confers therapeutic resistance to TEAD inhibitors." (PMID 36347861, 2022). "The present study was designed to analyse the relationship between VGLL3 and EMT phenotypes in cancer cells." (PMID 35366053, 2022). "In conclusion, we found that VGLL3 promotes E‐cadherin repression and cell motility via HMGA2 in TGF‐β‐stimulated and mesenchymal cancer cells." (PMID 35366053, 2022). "Consistently, a recent study using a panel of cancer cell lines found that treatments with the TEAD inhibitor MGH-CP1 and YAP/TAZ silencing both promoted the VGLL3-mediated transcriptional activation of SOX4/PI3K/AKT signaling, which contributed to resistance to MGH-CP1." (PMID 38473214, 2024). "We hypothesized that TEAD inhibition leads to VGLL3-mediated PIK3C2B and SOX4 induction, resulting in AKT activation, promotion of cell survival, and compromising the effects of TEAD–YAP blockade in cancer cells." (PMID 36347861, 2022). "We speculate that VGLL3 functions as an inducer of partial EMT in cancer cells by stimulating cell motility and accelerating cancer progression." (PMID 35366053, 2022).